INS (insulin)
Diseases named in the same sentence as INS in open-access papers (continued):
Sharing a sentence is not in itself a finding about the gene and the disease.
diabetes (continued). "In addition to obesity and diabetes, the insulin resistance of adipose tissue and free fatty acid flux to the liver has been shown to lead to the activation of liver macrophages during MAFLD." (PMID 36531832, 2022). "Specifically, macrophage infiltration and pro-inflammatory activation has been associated with synovitis/fat pad fibrosis severity in the knee joints of osteoarthritis patients, as well as pancreatic islet viability/insulin secretion capacity in diabetes patients." (PMID 36552765, 2022). "In conclusion, adding exenatide to basal insulin in early T2DM does not further enhance underlying beta-cell function or the capacity to achieve diabetes remission, despite yielding on-treatment glycemic benefit." (PMID 36244997, 2022). "The beneficial effect of CHP containing food in diabetes was experimentally confirmed by at least three independent studies which showed that consumption of raw vegetables and yeast hydrolysates improves insulin sensitivity and glucose tolerance." (PMID 35565743, 2022). "Through glucose neurotoxicity and a defective insulin signaling system, hyperglycemia, insulin dysregulation, and oxidative stress were connected to neuronal apoptosis, neuroinflammation, and the development of neurodegeneration in diabetes." (PMID 35682821, 2022). "This pattern of insulin release is beneficial because a higher level of glucose is being consumed continuously while insulin is being released at peak levels, which is useful for the clinical treatment of diabetes." (PMID 35268787, 2022). "Aging, urbanization, and lifestyle factors are causative factors of type 2 diabetes mellitus (T2DM), which is a chronic metabolic disorder characterized by insulin insensitivity as a result of insulin resistance, declining insulin production, and eventual pancreatic β-cell failure." (PMID 35727613, 2022). "Moreover, improving peripheral metabolism in obese and diabetes subjects through dietary restrictions has been shown to restore CNS insulin sensitivity, and treating CNS insulin sensitivity improves peripheral metabolism." (PMID 35741464, 2022). "Data from clinical trials aimed at evaluating the efficacy of combination therapy with metformin/pioglitazone/exenatide versus sequential addition of metformin followed by glipizide and insulin in patients with long-standing type 2 diabetes mellitus (T2DM) have recently been recently published." (PMID 36295635, 2022). "Patients with this type of diabetes require 100 times or more insulin than the typical requirement." (PMID 36678512, 2022). "Furthermore, height rate was positively associated with development of T1D (HR = 1.80 [95% CI = 1.15, 2.81]) in the analyses from seroconversion with insulin autoantibody to diabetes." (PMID 35244713, 2022). "Diabetes mellitus, commonly known as diabetes, is a chronic disease that predominantly changes the metabolism of macronutrients (e.g., carbohydrates, proteins, and fats), electrolytes, and water due to abnormal insulin secretion." (PMID 36518402, 2022). "As expected, basal glycemia, insulin, HbA1c (glycated hemoglobin), and markers of oxidative stress (nitrotyrosine and 8-iso-PGF2a (8-iso prostaglandin F2a)) were increased in diabetes, and FMD (flow-mediated vasodilation; a marker of endothelial function) was decreased." (PMID 35205155, 2022). "Poor insulin hexamer stability has proved limiting to its use in diabetes therapy." (PMID 36348051, 2022). "Co-delivery of B7-1wa and PPINS cDNA eliminates insulin responsiveness and improves diabetes." (PMID 36405706, 2022). "In the presence of maternal obesity and diabetes, increased birth weight could be a consequence of the trophic effects of hormones, including insulin and leptin, as well as a manifestation of either genetic predisposition or enhanced nutrient availability." (PMID 35197933, 2022).
diabetes (continued). "Treatment with intensive insulin therapy for the management of T1DM was established as the standard of care based on the results of the Diabetes Control and Complication Trial (DCCT) and can be administered with multiple daily injections (MDI) or an insulin pump (CSII)." (PMID 36141404, 2022). "This helps to preserve insulin production and minimises the impact of diabetes." (PMID 35603294, 2022). "On the other hand, Type 2 diabetes mellitus is more familiar and a major portion of diabetic patients (90 to 95%) are suffering from this dysfunction, which is categorized by peripheral insulin resistance and anomalies in the secretion of insulin." (PMID 35282429, 2022). "There are a few kinds of diabetes which include Type I (mainly autoimmune in nature) and Type II, which is attributed to a decrease in the response to insulin (like lower glucose uptake in the muscle and fat tissue), or upregulation of glucose production (in the liver)." (PMID 36557274, 2022). "Moreover, hepatic insulin resistance impairs suppression of glucose production by insulin in hepatocytes, participating in the chronic increase in glycaemia characteristic of diabetes." (PMID 35185804, 2022). "In addition, the overexpression of SREBP2 can lead to an alteration in insulin secretion, a reduced number of pancreatic beta cells, diabetes, low weight, increased total cholesterol (TC) in blood and tissues, and non-alcoholic hepatic steatosis." (PMID 35625914, 2022). "Such a system could significantly aid in T1D care and eventually be used in various diabetes management wearables, such as insulin pumps and CGMs." (PMID 35862181, 2022). "UCPCR is a simple and less invasive method of assessing endogenous insulin secretion and may be potentially relevant in identifying different types of diabetes in resource-limiting settings where complex laboratory methods are scarce or expensive." (PMID 35462815, 2022). "Therefore, to evaluate the interaction between GV, food intake, and diabetes mellitus treatment regimen, we enrolled 16 patients with type 2 diabetes who were under a pre-mixed insulin regimen and applied the first CGM." (PMID 36463197, 2022). "A large cohort trial, The Diabetes Control and Complications Trial (DCCT), demonstrated the importance of intensive insulin treatment therapy in the reduction of many of these diabetes-related complications, in comparison to the more traditional conventional insulin therapy treatment." (PMID 36083870, 2022). "In addition, the signaling pathways of prolactin, Rap1, Ras, and FoxO are involved in insulin production or the pathology of diabetes." (PMID 36159557, 2022). "The modulation of the NRF2/KEAP1 pathway improves insulin sensitivity in diabetes and obesity." (PMID 35955599, 2022). "Odds ratio of Non-insulin hypoglycemic agents (vs diet only or insulin) for each diabetes subgroup." (PMID 36457559, 2022). "In a previous school survey, more than one-third of adolescents hid the fact that they had diabetes at school, which could lead to reduced glucose testing and insulin omission, especially during schooldays." (PMID 36568429, 2022). "Multivariate linear regression confirms a significant association between insulin sensitivity and better mitochondrial function (beta = 0.54, p = 0.003), independent of age, duration of diabetes, and smoking." (PMID 36135178, 2022). "A total of 245 insulin requests were made as some people with diabetes used 2 types of insulin." (PMID 35436214, 2022). "CPOE order sets aggregate orders related to a specific management issue, such as a medical diagnosis of diabetes or use of insulin in the inpatient setting, facilitating succinct, effective, and efficient ordering of medications and treatments for patients in the hospital setting." (PMID 35917098, 2022).
diabetes (continued). "The study has shown that, in diabetics, decrease in insulin is not as harmful as an increase in glucagon, as insulin deficient animals that were simultaneously knocked out of the glucagon receptor were normoglycemic." (PMID 35211170, 2022). "It is possible to identify other types of diabetes, defined as “other specific types of diabetes”, due to factors like genetic defects of both the β-cell and insulin metabolism, diseases of the exocrine pancreas, endocrinopathies, infections, drugs, and chemicals." (PMID 36289735, 2022). "Type 1 diabetics’ risk factors include age, severity of diabetic retinopathy (DR) and proteinuria; Type 2 diabetics’ risk factors include prolonged duration of diabetes, lack of metabolic control and use of insulin." (PMID 35806147, 2022). "Poor glycemic control is often associated with lack of sufficient SMBG and insulin dosing when there is significant family conflict and increased diabetes-related distress." (PMID 36992766, 2022). "Generally, diabetes is associated with dyslipidemia due to the insufficient or absence of insulin which participates in the regulation of lipid metabolism." (PMID 36080407, 2022). "However, approximately 90% of all diagnosed and reported cases of diabetes are type-2-diabetes and occur when insulin production is inadequate or when there is peripheral resistance to the action of insulin." (PMID 36359988, 2022). "This leads to an environment of high blood sugar and insulin insensitivity, which over time may contribute to developing higher risks of diabetes." (PMID 36078455, 2022). "Given the significant role that exercise plays in the prevention and management of diabetes, it is reasonable to hypothesize that these myokines play a considerable role in maintaining insulin sensitivity and managing blood glucose." (PMID 36479347, 2022). "As defined by the American Diabetes Association(ADA), the condition is a group of metabolic diseases that are characterized by chronic hyperglycaemiadue to a deficiency in insulin secretion, insulin's action, or both." (PMID 35265127, 2022). "Specifically, obesity/diabetes/insulin-related pathways and pancreatic cell injury pathways might be responsible for pancreatic carcinogenesis in fatty infiltration and fatty replacement, respectively." (PMID 35327494, 2022). "A previous systematic review measuring the effects of GLN supplementation on metabolic variables in diabetes mellitus showed that it could decrease fasting blood glucose, postmeal glucose, and triglyceride levels and increase insulin production." (PMID 36578449, 2022). "Using the fixed oil obtained from fresh O. tenuiflorum leaves, it was observed to significantly lower diabetically elevated blood glucose levels, serum lipid profiles, and serum insulin levels in streptozotocin-induced type 1 diabetes mellitus rats within three weeks." (PMID 36014373, 2022). "Furthermore, previous studies have shown that intensive insulin therapy has the potential to improve glycemic control and alleviate diabetes but also leads to some side effects, such as hypoglycemia and weight gain." (PMID 35966093, 2022). "Targeting the flipping efficiency of Stx2 profoundly modulates secretion, which could restore the impaired insulin secretion in diabetes." (PMID 36316316, 2022). "Dysregulation of insulin maturation, secretion, or degradation can result in diabetes." (PMID 35628387, 2022). "These states can, over time, impair insulin production and sensitivity and lead to diabetes." (PMID 35455055, 2022). "This implies that the PUFA content of a cell membrane can influence insulin action and insulin sensitivity, and PUFAs may, therefore, have an important role in the pathobiology of diabetes mellitus." (PMID 35669071, 2022). "Several market-available treatments for diabetes could be used, such as insulin therapy, synthetic drugs, herbal drugs, and transdermal patches, to help control blood sugar." (PMID 35684164, 2022).
diabetes (continued). "• Treatment with GH can decrease insulin sensitivity, especially at higher doses.• Patients with undiagnosed diabetes or pre-diabetic patients may exhibit worsened glycemic control with GH treatment." (PMID 36619571, 2022). "We also collected follow-up data after discharge and reported data from two cohorts (before and after use of corticosteroids for SARS-CoV-2 infection in people with diabetes who required insulin as a new treatment for managing their diabetes during hospitalisation)." (PMID 35256883, 2022). "Notably, the inhibition of Dll4‐Notch signaling was recently shown to drive differentiation of insulin‐producing cell progenitors, induce β‐cell proliferation and confer protection against streptozotocin‐induced diabetes." (PMID 35986504, 2022). "Finally, using syngeneic and xenogeneic transplant models, we demonstrated that after VR, islets remain viable in vivo, produce insulin, respond to glycemic challenge and cure diabetes." (PMID 35288694, 2022). "Diabetes mellitus (DM) is a group of metabolic disorders, which is described by an absolute or relative shortage in insulin secretion and/or insulin action accompanied by persistent hyperglycemia and perturbations of carbohydrate, lipid, and protein metabolism." (PMID 35529919, 2022). "Diabetes mellitus is a long-term metabolic syndrome caused by the lack of and/or resistance to insulin." (PMID 36544223, 2022). "Butyrate increases insulin sensitivity and reduces glucagon production in the pancreas and stimulates glucose uptake in the muscle and adipose tissue, so butyrate supplementation is important to treatment or prevention of diabetes." (PMID 36014875, 2022). "Both calibration models and performance of GlucoBeam system were checked and assessed as comparable to the earlier scanning CGM FreeStyle Libre (Abbott Diabetes Care) system by a very recent report, performing the research on a cohort of 15 insulin-treated subjects with type 1 diabetes." (PMID 36226124, 2022). "In diabetes or obesity with hyperinsulinemia, increased apelin is a compensatory mechanism in which it not only inhibits pancreatic secretion but also leads to insulin sensitivity and glucose uptake into insulin-independent muscle tissue and then leads to a decrease in apelin levels." (PMID 36093083, 2022). "Furthermore, endogenous and exogenous melatonin ameliorates diabetes and related metabolic dysfunction by regulating insulin secretion and protecting against ROS." (PMID 36056774, 2022). "There were seven studies that assessed a range of metabolic co-morbidities in addition to NAFLD, including one or more of the following: type 2 diabetes mellitus, insulin resistance, higher fasting insulin levels, obesity, hypertension, hypercholesterolaemia, hypertriglyceridemia." (PMID 36661654, 2022). "Genetically-modified mice lacking Dsg2 were examined for islet cell mass, insulin production, responses to glucose, susceptibility to a streptozotocin-induced mouse model of hyperglycaemia, and ability to cure diabetes in a syngeneic transplantation model." (PMID 36309486, 2022). "Considering the high prevalence of diabetes mellitus and insulin treatments, the incidence rate of cutaneous amyloidosis might have been underestimated." (PMID 35563343, 2022). "As a result, diabetes can be either insulin-dependent or insulin-independent." (PMID 36359308, 2022). "Thus, it is plausible to initiate insulin therapy in patients with diabetes of long duration and suboptimal glycemic control, as shown in the current study (mean duration 8.7–12.1 years, mean HbA1C 8.84–9.50%)." (PMID 36559020, 2022). "“And I'd say roughly 50% would end up needing insulin education” (F-diabetes educator—30 yrs)." (PMID 35782628, 2022). "PC development on the basis of diabetes depends on the long-term persistence of high intra-pancreatic insulin levels that can promote survival and proliferation of any transformed cells that may arise in pancreas." (PMID 35893093, 2022).
diabetes (continued). "Moreover, the inhibition of PHD3 improves insulin sensitivity and ameliorates diabetes by specifically stabilizing HIF-2α." (PMID 35625760, 2022). "In real life, where people with T1D face challenges of daily diabetes management, SC insulin and CSII could differ in terms of effectiveness, ease of use, and short and long term outcomes." (PMID 35690827, 2022). "In a rodent pre-diabetes model, hyperexcitability was found in the tibial nerve which correlated with weight, insulin resistance, and insulin and leptin levels, suggesting that metabolic changes may drive early axonal dysfunction." (PMID 35565656, 2022). "Utilizing SC in cell-based delivery of endogenous insulin could overcome the major hurdles of transplant rejection and toxic immune suppression to provide more effective treatment of diabetes mellitus." (PMID 36555540, 2022). "Furthermore, there was a lack of individual patient-level data as well as a lack of systematic collection of insulin/glucose measurements and diabetes medication or insulin use, which limited the extent of analysis." (PMID 35441656, 2022). "Four out of five patients (80%) had type-2 diabetes, 23/35 (66%) took no antidiabetic drugs at baseline, 8/35 (23%) were already on oral diabetes medication, 3/35 (8.6%) were on subcutaneous multi-daily insulin injections, and one patient had combined both oral diabetes medication and basal insulin." (PMID 36289683, 2022). "To this end, we used data from the Dehgolan Prospective Cohort Study (DehPCS) to assess the validity of self-reported diabetes based on the reference criteria, including the history of taking oral anti-diabetic drugs, insulin injection, or high fasting blood sugar (FBS)." (PMID 35619088, 2022). "In recent years, the popular etiology theory of diabetes inflammation believes that diabetes is a kind of natural immune and low-grade inflammatory disease, and cytokine-mediated inflammatory response affects insulin secretion by inducing apoptosis and dysfunction of pancreatic β-cells." (PMID 35399638, 2022). "However, non-invasive approaches to insulin delivery will redefine current treatment of diabetes and will be widely acceptable to patients and healthcare institutes, particularly if they are cost-effective and patient-friendly." (PMID 35890301, 2022). "Therefore, we conducted a prospective study with up to 47 months of follow‐up of T2DM patients to investigate the different characteristics of basal and premixed insulin use in real‐world practice at 10 diabetes centers in China." (PMID 35023626, 2022). "Although the most appropriate treatment method is insulin preparations accessible to monitor the hyperglycemic condition, subjects with diabetes have to face various difficulties involving some complications in administering insulin, inconvenience after injection, etc.." (PMID 35723344, 2022). "This may be a reminder of the importance of standardized insulin therapy, particularly in diabetes patients with CRD in the future." (PMID 36093107, 2022). "Type 1 diabetes mellitus (T1DM) is a chronic disease requiring lifelong insulin treatment." (PMID 35162654, 2022). "However, until studies are conducted comparing insulin function in migraine patients with obesity or diabetes versus obese or diabetes controls, it remains difficult to attribute changes in insulin resistance solely to migraine." (PMID 36175833, 2022). "The results of this survey study illustrate that T1DM patients seek a diabetes health app that integrates many relevant factors and functions, such as glucose monitoring, insulin delivery, nutrition, physical activity, etc. in a single app and that allows for interoperability with other apps." (PMID 35673501, 2022). "The clinical picture of fetal growth restriction in an insulin‐treated diabetic pregnant woman with a strong maternal family history of young, non‐obese and uncomplicated diabetes prompted the endocrinologists to consider GCK‐MODY in this patient and her family." (PMID 36483860, 2022).